ENSG00000277764
Gene: Miscellaneous RNA gene on chromosome 2 (70,900,155 to 70,900,351, forward strand). Ensembl gene ENSG00000277764.
Gene Ontology:
Biological process: regulation of cell cycle